CFTR (CF transmembrane conductance regulator)
Diseases named in the same sentence as CFTR in open-access papers (continued):
Sharing a sentence is not in itself a finding about the gene and the disease.
cystic fibrosis (continued). "In Germany, Cystic Fibrosis is diagnosed by Newborn Screening (NS) comprising immunoreactive trypsinogen (IRT)/Pancreatitis-Associated Protein (PAP) measurements, followed by targeted genetic testing for the most common CFTR variants." (PMID 41399729, 2025). "In day 14 and day 15 explants, robust responses to Amil indicated epithelial sodium channel (ENaC) activity, and responses to FSK and cystic fibrosis transmembrane regulator (CFTR) inhibitor–172 (CFTRinh-172) indicated CFTR activity, again aligning with previous work." (PMID 40279421, 2025). "The advent of CFTR modulators, particularly the triple combination therapy elexacaftor–tezacaftor–ivacaftor (ETI), has revolutionized the management of cystic fibrosis." (PMID 41070102, 2025). "Cystic fibrosis arises primarily from mutations in the CFTR gene, nearly 10% are nonsense mutations, which introduce premature termination codons (PTCs) within the CFTR mRNA, leading to truncated, non-functional CFTR protein and a complete loss of chloride channel activity at the epithelial surface." (PMID 41550651, 2025). "Small molecules that correct defective trafficking of the CFTR chloride channel may be the most well-known success, with drug combinations that simultaneously improve the delivery of CFTR to the plasma membrane and potentiate channel opening in routine clinical use for cystic fibrosis." (PMID 40559528, 2025). "Mutation-agnostic treatments such as airway gene therapy have the potential to treat any individual with cystic fibrosis, irrespective of their CF transmembrane conductance regulator (CFTR) gene variants." (PMID 39183346, 2024). "It was further suggested that patients with CF could be given a urine pH test after oral HCO3- loading to validate the efficacy of CFTR modulators in treating cystic fibrosis." (PMID 39170739, 2024). "ABPA has been typically described in individuals with asthma or cystic fibrosis and may be the sole manifestation of a CF transmembrane conductance regulator (CFTR)-related disorder (CFTR-RD)." (PMID 39131200, 2024). "In CF, the cystic fibrosis transmembrane conductance regulator (CFTR) ion channel is dysfunctional." (PMID 39461969, 2024). "CF is a genetic disease caused by absent or aberrant function of the cystic fibrosis transmembrane conductance regulator (CFTR), which leads to airway periciliary dehydration, increased mucus viscosity, and decreased mucociliary clearance." (PMID 38440830, 2024). "In addition to the remaining ACE2 expression, another possible explanation for this heterogeneity in COVID-19 susceptibility could be that that independently of ACE2, the quality of life for people with cystic fibrosis may depend on contributions from non-CFTR modifier or bystander genes." (PMID 39043712, 2024). "In 2018, Translate Bio, Inc. conducted a Phase II trial (NCT03375047) involving adults and seniors aged 18 years or older with cystic fibrosis to investigate the safety and therapeutic efficacy of MRT5005—an aerosol containing codon-optimized CFTR mRNA." (PMID 39543114, 2024). "However, it is noteworthy that individuals with CF commonly display gastrointestinal (G-I) manifestations due to the substantial presence of the cystic fibrosis transmembrane conductance regulator (CFTR) protein in the intestinal tract." (PMID 38275475, 2024). "Cystic fibrosis is an autosomal recessive disorder caused by various mutations in the cystic fibrosis transmembrane conductance regulator (CFTR) gene, but the ΔF508 mutation (a deletion of the phenylalanine at amino acid position 508 in the protein) accounts for 70% of CF patients." (PMID 38952711, 2024). "For instance, cystic fibrosis (CF, OMIM #219700) is an autosomal recessive monogenic disorder caused by mutations in the cystic fibrosis transmembrane conductance regulator (CFTR) for which a significant diversity of pathogenic variants was found in patients of different ancestry." (PMID 39202055, 2024).
cystic fibrosis (continued). "The combination of elexacaftor/tezacaftor/ivacaftor (ETI, Trikafta) reverses the primary defect in cystic fibrosis by improving CFTR-mediated Cl− and HCO3− secretion by airway epithelial cells (AECs), leading to improved lung function and less frequent exacerbations and hospitalizations." (PMID 39437760, 2024). "In contrast, adrenergic fibers influence the Cystic Fibrosis Transmembrane Conductance Regulator (CFTR) chloride channels, which have been extensively studied in the context of cystic fibrosis." (PMID 39529803, 2024). "Interestingly, cystic fibrosis transmembrane conductance regulator (CFTR) modulators used in CF also have been shown to alter intestinal microbiota and have been associated with celiac disease (CD) in small studies." (PMID 38800303, 2024). "CF is caused by a mutation in the cystic fibrosis transmembrane conductance regulator (CFTR) gene resulting in dysfunction or absence of the corresponding CFTR protein." (PMID 39335678, 2024). "Currently, UK newborn blood spot screening for cystic fibrosis involves measuring immunoreactive trypsinogen (IRT), with analysis of CFTR (initially limited, then potentially more extensive) for babies with IRT levels over a specified cut-off." (PMID 38550936, 2023). "Cystic fibrosis, the most common life-limiting genetic disease in Caucasians, is characterized by dysfunction of the cystic fibrosis transmembrane conductance regulator (CFTR) protein." (PMID 37259368, 2023). "Cystic fibrosis is caused by mutations in the CF transmembrane conductance regulator (CFTR) gene resulting in dysfunctional or absent CFTR protein." (PMID 36875141, 2023). "BMI = body mass index; RCT = randomized controlled trial, CFTR = cystic fibrosis transmembrane conductance regulator; ETI = elexacaftor/tezacaftor/ivacaftor; LS = least squares mean; CFRD = cystic fibrosis related diabetes." (PMID 37511806, 2023). "Pathogenic variants in the CFTR gene (Cystic Fibrosis Transmembrane conductance Regulator, OMIM: 602421) are known to cause one of the most common autosomal recessive monogenic diseases, Cystic Fibrosis (CF, OMIM: 219700)." (PMID 37510311, 2023). "Similarly, development of orphan-designated drugs that target the basic defect in cystic fibrosis —the CF transmembrane conductance regulator (CFTR) ion channel—has resulted in significantly increased life expectancy for patients with this devastating disease." (PMID 37353796, 2023). "The lack of normal CFTR channel activity is associated with chronic infection and inflammation which are the primary causes of declining lung function in Cystic Fibrosis patients." (PMID 37443798, 2023). "Whether CF macrophage dysfunction is related directly to Cystic Fibrosis Transmembrane Conductance Regulator (CFTR) in macrophages or an indirect consequence of chronic inflammation and mucostasis is a subject of ongoing debate." (PMID 37491532, 2023). "In CF, it remains detectable despite treatment with highly effective modulator therapy (HEMT) that corrects the underlying dysfunction in the cystic fibrosis transmembrane conductance regulator (CFTR) ion channel." (PMID 37039381, 2023). "It remains to be seen whether the implementation of lifelong CFTR (cystic fibrosis transmembrane conductance regulator) modulation will change the temporal evolution of the CF airway metagenome." (PMID 36892308, 2023). "They started by characterizing natural mutations in F9 exon 5, CFTR exon 12 and SMN2 exon 7 associated with exon skipping in Hemophilia B, Cystic fibrosis, and Spinal muscular atrophy (SMA), respectively and then tried its therapeutic splicing rescue by using different ExSpeU1s." (PMID 37834063, 2023). "CFTR and ENaC play essential roles in ion and fluid transport in numerous epithelial tissues, dysfunction of which leads to diseases such as cystic fibrosis, secretory diarrhoea and kidney disease." (PMID 36205782, 2023).
cystic fibrosis (continued). "There are many potential mechanisms that could contribute to sarcopenia in CF including physical inactivity, inflammation, malnutrition, and cystic fibrosis transmembrane conductance regulator (CFTR) specific muscle dysfunction." (PMID 36997883, 2023). "In 1989, molecular biology development led to the discovery of the CFTR (Cystic Fibrosis Transmembrane Regulator) gene and also rapidly to the first report of a variation, F508del, which is now identified in 70% of people with CF (pwCF)." (PMID 37445855, 2023). "Elexacaftor/Tezacaftor/Ivacaftor (ELX/TEZ/IVA) is a new CFTR (Cystic Fibrosis Transmembrane Conductance Regulator) modulator treatment, used over the last few years, which has shown an improvement in different clinical outcomes in patients with cystic fibrosis." (PMID 36980112, 2023). "consider the role of sphingolipids in the homeostasis of cystic fibrosis transmembrane conductance regulator (CFTR) and the potential of manipulating sphingolipid metabolism to ameliorate cystic fibrosis." (PMID 37589211, 2023). "Mutation targeted therapy in cystic fibrosis is still not eligible for all CF subjects, especially for cases carrying rare variants such as the CFTR genotype W57G/A234D (c.169T>G/c.701C>A)." (PMID 38026150, 2023). "A major unmet need in the cystic fibrosis therapeutic landscape is the lack of effective treatments for nonsense CFTR mutations, which affect approximately 10% of CF patients." (PMID 38019847, 2023). "The absence or dysfunction of CFTR in the alveolar epithelium lining caused decreased Cl- secretion and increased Na+ reabsorption, suggesting that CS-mediated COPD might be due, at least in part, to reduced CFTR activity and related cystic fibrosis and pulmonary inflammation." (PMID 36226596, 2023). "CFTR-mediated Cl− and HCO3− secretion are thought to control mucus viscosity in multiple cystic fibrosis-affected organs by respectively regulating fluid secretion and Ca2+ chelation required for proper unfolding of mucus." (PMID 37730992, 2023). "Indeed, in the search for cystic fibrosis transmembrane conductance regulator (CFTR) therapies, HBECs were seen as the “gold standard” in preclinical studies." (PMID 37048070, 2023). "The keywords used to conduct the search were cystic fibrosis, CF, elexacaftor (ELX), tezacaftor (TEZ), ivacaftor (IVA), CF triple therapy, AND CFTR modulators." (PMID 36284811, 2022). "CFTR is an anion and intracellular ligand-gated channel related to cystic fibrosis." (PMID 36060694, 2022). "The specific importance of CFTR activity in maintaining fluid transport in the allergic airway is reinforced by the observation that CFTR gene mutations are found in patients with asthma or nasal polyps (without cystic fibrosis) at higher rates than in healthy control populations." (PMID 35608904, 2022). "Cystic fibrosis (CF; OMIM # 219700) is a genetic autosomal recessive disease, caused by a defect in the cystic fibrosis transmembrane conductance regulator (CFTR) protein, an anionic channel present in the apical membrane of various epithelial cells, where it regulates electrolytic exchanges." (PMID 35887806, 2022). "CF is caused by a mutation in the cystic fibrosis conductance regulator (CFTR) gene, resulting in an absent or dysfunctional CFTR protein-altering chloride transport through the apical epithelial membrane." (PMID 36292016, 2022). "Cystic Fibrosis is an autosomal, recessive disorder, arising from defects in the CF transmembrane conductance regulator (CFTR) gene (Riordanet al., 1989) and affects many aspects of function and daily living for people living with CF (PwCF) (Elborn, 2016;Sawickiet al., 2011)." (PMID 36091185, 2022). "Here, we analyzed SARS-CoV-2 replication in wild-type and CFTR-modified human bronchial epithelial cell lines and primary cells to investigate SARS-CoV-2 infection in people with cystic fibrosis." (PMID 35456026, 2022). "Patients with CFTR mutations may develop pancreatitis with or without cystic fibrosis." (PMID 35844741, 2022).
cystic fibrosis (continued). "Activation of CFTR requires ATP and phosphorylation by PKA, and dysregulation of CFTR mediated salt and water homeostasis can lead to cystic fibrosis." (PMID 36012518, 2022). "Cystic Fibrosis is a life-limiting recessive disease caused by mutations in the CF Transmembrane Conductance Regulator (CFTR) gene that result in absent or dysfunctional CFTR protein." (PMID 36467478, 2022). "In experiments with the cystic fibrosis cell line IB3-1, the CFTR-corrected C38 bronchial epithelial cell line, and the normal primary human bronchial epithelial cells, when ARSB was silenced, IL-8 secretion declined following exposure to TNF-α." (PMID 36361933, 2022). "Therapy with CFTR modulators is the most effective method of treating cystic fibrosis." (PMID 36286063, 2022). "Although CF micro-environment is obviously an important element to program neutrophils, endogenous neutrophil disturbances due to cystic fibrosis transmembrane conductance regulator (CFTR) defect remain to be studied." (PMID 36248793, 2022). "Cystic fibrosis, an autosomal recessive genetic multiorgan disease, is caused by an absent or dysfunctional CF transmembrane conductance regulator (CFTR) channel that mainly mediates chloride anion transport across the apical membrane of epithelial cells." (PMID 34831090, 2021). "Interestingly, this amino acid is analogous to F508 in CFTR/ABCC7, the mutation of which is responsible for diminished trafficking of CFTR, and ultimately the cystic fibrosis phenotype." (PMID 33801813, 2021). "The aim of this work is to improve our knowledge of the CFTR gene regulation, and to identity factors that could impact the CFTR gene expression, and potentially account for the variability of the clinical presentation of cystic fibrosis as well as CFTR-related disorders." (PMID 33807548, 2021). "The genetic disease cystic fibrosis has been transformed by drugs that act on the basic CF defect, impaired anion conductance of the cystic fibrosis transmembrane conductance regulator (CFTR) channel." (PMID 34903059, 2021). "By carrying a full-length CFTR cDNA of 4.5-kb, it could rescue approximately one third of the cystic fibrosis transmembrane conductance regulator (CFTR) function in the CF phenotype of human airway epithelia." (PMID 34220786, 2021). "For example, cystic fibrosis—the defect of the cystic fibrosis transmembrane conductance regulator (CFTR) genes—leads to the accumulation of succinate in the lungs, which favors the colonization and survival of P. aeruginosa, as this microorganism can utilize it as a nutrient source." (PMID 33406652, 2021). "While the primary cause of death in CF patients is lung infections, intestinal blockages are observed in CF mouse models instead due to the lack of a functional protein, cystic fibrosis transmembrane conductance regulator (CFTR)." (PMID 34451881, 2021). "The best known manifestation of chloride channel dysfunction, namely CFTR, is cystic fibrosis; however, it is also known that CFTR plays a role in cardioprotection against ischemia/reperfusion injury and the development of CF-related diabetes." (PMID 34832033, 2021). "Cystic fibrosis [OMIM (Online Mendelian Inheritance in Man: #219700)] is a monogenic disease, which is caused by the occurrence of more than 2,000 genetic variants for the protein CF transmembrane conductance regulator (CFTR)." (PMID 34901273, 2021). "In cystic fibrosis, the latest development of modulators, correctors and potentiators, of the defective gene product—the cystic fibrosis transmembrane conductance regulator (CFTR)—has created important opportunities to influence the defective protein and its functions." (PMID 33800499, 2021). "Patients with cystic fibrosis are at increased risk of malnutrition and growth failure due to multiple factors as a result of suboptimal or absent function of the CFTR chloride channel protein." (PMID 34578785, 2021).
cystic fibrosis (continued). "Mutations in the CFTR gene that lead to premature stop codons or splicing defects cause cystic fibrosis and are not amenable to treatment by small-molecule modulators." (PMID 34520545, 2021). "The interplay between the cystic fibrosis transmembrane conductance regulator (CFTR) and the epithelial sodium channel (ENaC) in respiratory epithelia has a crucial role in the pathogenesis of cystic fibrosis." (PMID 33916525, 2021). "However, given the high prevalence of AWP associated with the genetic disease, physicians should have a high index of suspicion of CF or cystic fibrosis transmembrane regulator (CFTR)-related disease in pediatric patients with this presentation." (PMID 34007735, 2021). "the authors demonstrated that the loss of cystic fibrosis transmembrane conductance regulator (CFTR) delays resolution of inflammation by reducing neutrophil reverse migration in the context of sterile inflammation using a zebrafish model of cystic fibrosis." (PMID 34899746, 2021). "CFTR protein dysfunction directly leads to the clinical symptoms and signs of cystic fibrosis." (PMID 34778915, 2021). "Similarly, several published studies have shown that a small increase in CFTR function translates into improved lung function and survival for individuals with cystic fibrosis (CF, MIM# 219700), even in moderate to advanced stages of disease." (PMID 34099697, 2021). "Cystic fibrosis is a rare, genetic, chronic, multisystemic disease caused by a dysfunction of the CFTR gene (cystic fibrosis transmembrane conductance regulator), which alters ion transport in the apical membrane of epithelial cells in various organs and tissues." (PMID 34840486, 2021). "The CFTR protein is involved in the regulation of several ions transporters, including sodium channel, chloride/bicarbonate exchangers, proton exchangers and water channels, and its biallelic dysfunction is responsible for the Cystic Fibrosis phenotype." (PMID 33806855, 2021). "Recent studies have indicated a new actor playing a role in the pathogenesis of CD, the cystic fibrosis transmembrane conductance regulator (CFTR), linking CD to Cystic Fibrosis." (PMID 33917155, 2021). "Expression of USP10 in human airway epithelial cells is therefore protective for CFTR abundance and chloride secretion, which is beneficial to patients with pneumonia, chronic obstructive pulmonary disease (COPD), and cystic fibrosis." (PMID 33277473, 2020). "Cystic fibrosis is a genetic and multi-organ disease, caused by mutations in the cystic fibrosis transmembrane conductance regulator (CFTR) gene, resulting in lacked or reduced expression and function of protein." (PMID 33101035, 2020). "A Cystic Fibrosis Foundation Therapeutics funded study, maternal and fetal outcomes in the era of CFTR modulators (MAYFLOWERS) will prospectively evaluate the impact of the use of this class of drugs on the health of women with CF and their infants." (PMID 32825766, 2020). "Absence of mutations in DNAI1, DNAH5, and CFTR genes ruled out primary ciliary dyskinesia and cystic fibrosis." (PMID 32991486, 2020). "The arrival of cystic fibrosis transmembrane conductance regulator (CFTR) modulators as a new class of treatment for cystic fibrosis in 2012 represented a pivotal advance in disease management, as these small molecules directly target the upstream underlying protein defect." (PMID 32887484, 2020). "CFTR related pathogenic variants may be rarely recognized in Indians in view of the different phenotypes (including cystic fibrosis and congenital absence of vas deferens), variable clinical severity and lack of availability of sweat testing, and absence of new born screening." (PMID 33138774, 2020). "Cystic fibrosis transmembrane regulator (CFTR) modulators are a new class of therapy that targets the basic genetic defect and could dramatically change the landscape of CF care." (PMID 33013419, 2020).